ANGPTL3 (angiopoietin like 3)
Diseases named in the same sentence as ANGPTL3 in open-access papers (continued):
Sharing a sentence is not in itself a finding about the gene and the disease.
coronary atherosclerosis (8 papers, 2018 to 2024). Atherosclerosis of the coronary vasculature. "ANGPTL3 single-nucleotide polymorphisms and their haplotypes are associated with the severity of coronary artery atherosclerosis and the risk of CAD, as assessed by angiography." (PMID 32440963, 2020). "This study showed that the DOCK7 rs1748195 SNP and rs1748195G-rs12563308T haplotype were associated with an increased risk of CAD and the severity to coronary atherosclerosis, whereas the ANGPTL3 rs12563308 SNP was associated with a decreased risk of CAD." (PMID 29454388, 2018). "In the current study, we showed that the DOCK7 rs1748195 SNP and rs1748195G-rs12563308T haplotype were associated with an increased risk of CAD and the severity to coronary atherosclerosis, whereas the ANGPTL3 rs12563308 SNP was associated with a decreased risk of CAD." (PMID 29454388, 2018). "Sun and colleagues (2021) showed that circulating levels of ANGPTL3 and ANGPTL4 were independent risk factors for coronary atherosclerosis." (PMID 39728292, 2024). "A concentration of ANGPTL3 over 30.5 ng/mL had a better sensitivity and specificity for the prediction of coronary atherosclerosis (sensitivity = 71.2%, specificity = 75.3%)." (PMID 34742313, 2021). "ANGPTL3 and ANGPTL4 were determined to be independent risk factors for coronary atherosclerosis with odds ratios (ORs) of 0.189 (95% CI 0.097-0.368, P < 0.001) and 3.625 (95% CI 1.873-7.016, P < 0.001), respectively." (PMID 34742313, 2021). "To answer this question, we performed a study of ANGPTL3 and ANGPTL4 in a cohort of patients with angina to clarify the associations of these proteins with coronary atherosclerosis severity." (PMID 34742313, 2021). "Using 30.5 ng/mL as a cutoff value, the sensitivity and specificity of ANGPTL3 for coronary atherosclerosis were 71.2 and 75.3%, and the area under the ROC curve was 0.785 (P < 0.01)." (PMID 34742313, 2021). "Finally, considering the results of the study, they do not explain the causal relationships, only showing an association between ANGPTL3, ANGPTL4 and coronary atherosclerosis severity." (PMID 34742313, 2021). "Does ANGPTL3 or ANGPTL4 represent a better predictive indicator for coronary atherosclerosis?" (PMID 34742313, 2021). "Individuals bearing loss-of-function mutations of the ANGPTL3 gene exhibit familial hypolipidemia and those with complete ANGPTL3 deficiency do not display signs of coronary atherosclerosis." (PMID 34440201, 2021). "This study comprehensively investigated the association between plasma ANGPTL3 or ANGPTL4 levels and coronary atherosclerosis severity, included the comparisons among different groups according to the degree of coronary stenosis and numbers of involved vessels." (PMID 34742313, 2021). "Increased ANGPTL3 or decreased ANGPTL4 shows an association with coronary atherosclerosis and, may become a predictor of coronary atherosclerosis in the future." (PMID 34742313, 2021). "ANGPTL3 could play a possible role in the development of coronary atherosclerosis, and ANGPTL4 may be a protective factor against atherosclerotic plagues." (PMID 34742313, 2021). "However, in the multivariable logistic regression analysis, ANGPTL3 and ANGPTL4 were determined to be independent risk factors for coronary atherosclerosis with odds ratios (ORs) of 0.189 (95% CI 0.097-0.368, P < 0.001) and 3.625 (95% CI 1.873-7.016, P < 0.001) respectively." (PMID 34742313, 2021). "The results showed that ANGPTL3 was significantly increased and ANGPTL4 was decreased in the coronary atherosclerosis group." (PMID 34742313, 2021). "ANGPTL3 or ANGPTL4 may become a convenient biomarker for screening and predicting coronary atherosclerosis in the future." (PMID 34742313, 2021). "Increased ANGPTL3 and decreased ANGPTL4 exhibit an essential association with coronary atherosclerosis severity regardless of their lipid levels." (PMID 34742313, 2021). "Both ANGPTL3 and ANGPTL4 were significantly related to coronary atherosclerosis." (PMID 34742313, 2021).
coronary atherosclerosis (continued). "Moreover, ANGPTL3 and ANGPTL4 may act as independent predictors of coronary atherosclerosis." (PMID 34742313, 2021).
dyslipidaemia (8 papers, 2018 to 2025). "Our study highlighted potential causal links between plasma proteins, dyslipidaemia, and CVDs in South Asians and highlighted protein targets, including CELSR2, PCSK9, ANGPTL3, and Apolipoprotein(a) (LPA)." (PMID 40689090, 2025). "APOC3, ANGPTL3, and ANGPTL4 are circulating proteins that are actively pursued as pharmacological targets to treat dyslipidaemia and reduce the risk of atherosclerotic cardiovascular disease." (PMID 38895109, 2024). "These associations included ACVRL1 and ENG with hereditary haemorrhagic telangiectasia, GRN with dementia, NOTCH1 with chronic lymphocytic leukaemia, PCSK9 and ANGPTL3 with dyslipidaemia, and others." (PMID 37794183, 2023). "One of the new possible targets for the treatment of dyslipidaemia is angiopoietin-like 3 protein (ANGPTL3), which is currently one of the main focal points of lipidology pharmaceutical studies." (PMID 35890138, 2022). "Likewise, the ANGPTL3-dyslipidaemia signal improved from P = 8.73 × 10−9 (OR = 0.58; 95% CI, 0.48 to 0.70) to P = 9.62 × 10−17 (OR = 0.57; 95% CI, 0.50 to 0.66) in the ptvolink model." (PMID 37794183, 2023). "ANGPTL3 deficiency is traditionally associated with reduced cardiovascular risk and serum lipid concentrations; as a consequence, the inhibition of ANGPTL3 by evinacumab may be a new therapeutic option for the management of dyslipidaemia." (PMID 34572264, 2021). "Briefly, APOE and LPA are components of LDL-C while ANGPTL3 and PCSK9 are known drug targets for dyslipidaemia treatment." (PMID 40689090, 2025). "Our study confirmed key proteins (PCSK9, ANGPTL3, LPA), identified potential novel targets (GSTA1, GSTA3, EPPK1, PECR, and PLA2G15), and strengthened evidence for CELSR2 and GAS6 in dyslipidaemia." (PMID 40689090, 2025).
myocardial infarction (8 papers, 2018 to 2025). Gross necrosis of the myocardium, as a result of interruption of the blood supply to the area, as in coronary thrombosis. "In case–control analyses without genetic typing, individuals in the lowest tertile of circulating ANGPTL3 also exhibited significantly lower myocardial infarction risk (adjusted OR 0.65)." (PMID 41561063, 2025). "Subjects with low ANGPTL3 levels in the population present a significantly reduced risk of myocardial infarction compared to subjects with elevated ANGPTL3 plasma levels [29, 30••]." (PMID 34698927, 2021). "In broader populations, three lines of evidence—pedigrees, heterozygous deficiency in the general population, and plasma-level stratification in myocardial infarction case–control studies—converge on a protective effect: heterozygous ANGPTL3 LoF carriers had 34% lower CAD risk." (PMID 41561063, 2025). "ANGPTL3 has been shown to exert a pro-angiogenic ability and promote cardiac angiogenesis after myocardial infarction, indicating that ANGPTL3 administration is a promising approach for SCI repair." (PMID 33413639, 2021). "Individuals in the lowest tertile of circulating ANGPTL3 concentration, compared with the highest, had reduced odds of myocardial infarction." (PMID 32440963, 2020). "Another human population study showed that plasma ANGPTL3 levels were increased in myocardial infarction patients." (PMID 29440457, 2018).
hypobetalipoproteinemia (7 papers, 2017 to 2026). A group of lipoprotein metabolism disorders that are characterized by permanently low levels (below the 5th percentile) of apolipoprotein B and LDL cholesterol. "There has been significant interest in the role of ANGPTL3 in the lipid metabolism pathway, as individuals with loss of function of ANGPTL3 have hypobetalipoproteinemia, including 70% lower LDL-C levels." (PMID 35956226, 2022). "Another study by exome sequencing of 15,994 genes from two individuals of a family with hypobetalipoproteinemia identified two novel compound heterozygotes carrying the loss-of-function mutations S17X and E129X in the first exon of ANGPTL3." (PMID 34298929, 2021). "The S17X mutation in ANGPTL3 resulting in familial hypobetalipoproteinemia was first reported in an Italian family in 1991." (PMID 34298929, 2021). "LOF mutations in ANGPTL3 gene have been demonstrated in patients with familial hypobetalipoproteinemia and familial combined hypolipidemia." (PMID 28971105, 2017). "ANGPTL3 was initially identified from familial hypobetalipoproteinemia in humans due to its role as an inhibitor of both lipoprotein lipase and endothelial lipase." (PMID 38462608, 2024).
steatosis (7 papers, 2018 to 2025). Increased lipid within the cytoplasm of cells. "Although we did not determine the concentration of lipids and cholesterol in our samples, the HCV-dictated ANGPTL-3 levels remaining after viral eradication could be causally involved, at least in part, in shaping specific lipid species and steatosis after treatment." (PMID 34360721, 2021). "This study found that ANGPTL3 concentration was significantly and independently associated with NASH, but not in patients with simple steatosis." (PMID 29619113, 2018).
nephrotic syndrome (6 papers, 2015 to 2023). A collection of symptoms that include severe edema, proteinuria, and hypoalbuminemia; it is indicative of renal dysfunction. "Multivariate linear regression analysis was used to identify variables associated with urinary ANGPTL3/Cre in children with nephrotic syndrome." (PMID 37266537, 2023). "Multivariate linear regression analysis was utilized to identify variables associated with serum ANGPTL3 in children with nephrotic syndrome." (PMID 37266537, 2023). "The use of ANGPTL3 as a marker to assess the severity of nephrotic syndrome, based on previous basic experiments, back to clinical patients, provides some theoretical basis for future targeted therapy in patients with proteinuria in nephrotic syndrome." (PMID 37266537, 2023). "As far as I know, the greatest strength of our article is that for the first time, blood and urine specimens from nephrotic syndrome due to different glomerular diseases were included to detect the expression level of ANGPTL3." (PMID 37266537, 2023). "In future clinical translation, the level of ANGPTL3 in serum, urine will be used as a biomarker to better predict the development of nephrotic syndrome." (PMID 37266537, 2023). "It is suggested that serum ANGPTL3 and urinary ANGPTL3/Cre levels can reflect the degree of urinary protein leakage in patients with nephrotic syndrome and can be used as a marker to assess the severity of nephrotic syndrome in the process of treatment." (PMID 37266537, 2023). "This study aimed to analyzed the correlation between the levels of ANGPTL3 in serum and urine of patients with nephrotic syndrome and proteinuria, and assessed the severity of the patients' disease." (PMID 37266537, 2023). "High-throughput sequencing data revealed elevated expression of Angptl3 in kidney tissues of patients with nephrotic syndrome from more than 18,000 genes." (PMID 38149181, 2022). "And in patients with nephrotic syndrome, urinary ANGPTL3 showed better sensitivity than serum ANGPTL3, consider that serum ANGPTL3 is not only related to renal podocyte injury but is also influenced by the liver, urinary ANGPTL3 is mainly directly related to renal podocyte injury." (PMID 37266537, 2023). "Therefore, we analyzed the correlation between the levels of ANGPTL3 in serum and urine of patients with nephrotic syndrome and proteinuria, and assessed the severity of the patients' disease." (PMID 37266537, 2023). "Hence, whether ANGPTL3 level could be correlated with the proteinuria level, and assessment of disease severity of nephrotic syndrome (NS) remained to be investigated." (PMID 37266537, 2023). "Therefore, we hypothesized that elevated levels of ANGPTL3 in the blood and urine of patients with nephrotic syndrome may represent the severity of podocyte injury, as well as proteinuria." (PMID 37266537, 2023). "In addition, we analyzed 11 patients with nephrotic syndrome who had both serum, urine, and renal tissues, and our analysis revealed that the expression levels of ANGPTL3 in serum, urine, and glomeruli were strongly correlated with the severity of podocyte injury (to be published)." (PMID 37266537, 2023).
gastric cancer (5 papers, 2022 to 2026). A primary or metastatic malignant neoplasm involving the stomach. "Nevertheless, the role of ANGPTL3 in cancer progression was rely on the certain tumor type, where it has also been illustrated that ANGPTL3 assumed the role of tumor suppressor in gastric cancer." (PMID 37344779, 2023). "Here, we performed additional in vitro studies on the effects of ANGPTL3 on the biological behaviors of gastric cancer cells." (PMID 37344779, 2023). "Overall, ANGPTL3 may be a useful biomarker in gastric cancer, and the combination of “writer” METTL3 and ANGPTL3 exhibits an innovative m6A-dependent regulatory mechanism." (PMID 37344779, 2023). "Furthermore, the reduced ANGPTL3 mRNA and protein levels were also consistently found in conventional gastric cancer cell lines (AGS and HGC27)." (PMID 37344779, 2023). "Therefore, continued exploration of METTL3 or association of METTL3 with “specific sites” in ANGPTL3 mRNA might contribute to the development of new cancer therapies and lead to the development of a new pathway for effective METTL3 inhibition in gastric cancer." (PMID 37344779, 2023). "In gastric cancer, we found CTHRC1 was highly co-expressed with many factors, such as ACVRL1, ANGPTL3, ANGPTL4, NOTCH4, VEGFB, VEGFC etc., which have been proved to play an important role in angiogenesis in various cancer." (PMID 35928443, 2022). "Additionally, a report showed that ANGPTL3 and ANGPTL6 expression was lower in gastric cancer (GC) tissues compared to normal gastric tissues, while ANGPTL1, ANGPTL2, and ANGPTL4 were more highly expressed in GC tissues than in normal gastric tissue." (PMID 39708716, 2025). "More than that, we tested a significant negative correlation between METTL3 and ANGPTL3 in 62 pairs of gastric cancer tissues." (PMID 37344779, 2023).
liver disease (5 papers, 2011 to 2025). "Biomarkers previously associated with liver diseases and identified in our samples were among others: ANGPTL3, IGFBP2, SDC4, IL1RN." (PMID 21978410, 2011). "Since ANGPTL3 is exclusively produced by hepatocytes, we used adeno-associated virus 2/8 (AAV2/8), a well-established gene intervention for liver disease." (PMID 38462608, 2024). "There were statistically significant differences in ANGPTL-3 serum levels between the various stages of HCV-induced liver disease (p-value = 0.002), with the acute infection group demonstrating the highest concentration, with a median value of 563.6 ng/mL." (PMID 34360721, 2021). "Therefore, we investigated the putative effect of DAA administration on the serum concentration of ANGPTL-3 and ANGPTL-4, in clinical samples from various stages of HCV-induced liver disease." (PMID 34360721, 2021). "Importantly, ANGPTL-3 levels were not subjected to post-cure corrective adjustment in patients with advanced liver disease and after HCV clearance in vitro." (PMID 34360721, 2021).
mixed hyperlipidemia (5 papers, 2018 to 2025). "ANGPTL3 deficiency results in a dramatic reduction of the plasma concentration of TG and cholesterol, and loss of function mutations in ANGPTL3 are the cause of a recessive form of familial combined hyperlipidemia." (PMID 29619113, 2018). "Treatment with a single dose of the anti-ANGPTL3/8-specific monoclonal antibody LY3475766 resulted in robust, dose-dependent increases (almost ninefold) in circulating ANGPTL3/8 levels in participants with mixed hyperlipidemia." (PMID 40640392, 2025). "In a double-blind study of 48 patients with mixed hyperlipidemia, the human ANGPTL3/8 mAb reduced plasma TG levels by 70%, remnant cholesterol levels by 61%, LDL cholesterol levels by 36%, and APOB levels by 31%, while increasing HDL cholesterol levels by 26%." (PMID 37824203, 2023). "Nonetheless, ANGPTL3 inhibitors can lower the concentrations of atherogenic particles independently of LDL receptor function and, hence, may be used in mixed hyperlipidemia and HoFH." (PMID 40005962, 2025).
ovarian carcinoma (5 papers, 2021 to 2025). A malignant neoplasm originating from the surface ovarian epithelium. "The presence of PCa in men, similarly to the presence of ovarian cancer in that prior study, seems to disrupt the association between ANGPTL3 and HDL levels." (PMID 39888285, 2025). "Specifically, an increase in ANGPTL3 mitigates the proliferation of ovarian cancer cells in vitro and the metastatic potential of these cells." (PMID 39057711, 2024). "On the other hand, data regarding the role of ANGPTL3 in ovarian cancer are conflicting." (PMID 39057711, 2024). "Furthermore, ANGPTL3 promotes natural killer (NK) cell killing of ovarian cancer cells while also modulating the JAK/STAT3 pathway to influence metastasis and immune resistance." (PMID 39057711, 2024). "Previously, the distinct downregulation of ANGPTL3 was also observed in ovarian carcinoma." (PMID 34484467, 2021). "The present study aims to measure and report circulating levels of ANGPTL3, PCSK9 and Apo CIII in women with ovarian carcinoma (OC); all three lipid-modulating factors are the target of clinically available therapeutical monoclonal antibodies or antisense oligonucleotide therapy." (PMID 38414008, 2024).
diabetic nephropathy (4 papers, 2014 to 2023). "Particularly relevant to diabetic nephropathy, Angptl3 is expressed on podocyte foot processes, and its increased expression correlates with their effacement." (PMID 24827579, 2014). "Moreover, there is evidence for the influence of ANGPTL3 on renal function and kidney structure, but to our knowledge, there is no data on serum levels of ANGPTL3 in patients with diabetic nephropathy." (PMID 37312105, 2023).
endothelial dysfunction (4 papers, 2021 to 2025). In vascular diseases, endothelial dysfunction is a systemic pathological state of the endothelium (the inner lining of blood vessels) and can be broadly defined as an imbalance between vasodilating and vasoconstricting substances produced by (or acting on) the endothelium. "Our results provide evidence that obese children and adolescents encounter higher circulatory levels of ANGPTL2 and ANGPTL3 compared to normal-weight children, which might be associated with MetS and endothelial dysfunction." (PMID 34422408, 2021). "Cluster 1 (rapidly increasing TyG) likely reflects progressive dysregulation of LPL-mediated triglyceride clearance or elevated ANGPTL3/4/8 expression, promoting atherogenic lipoprotein accumulation and endothelial dysfunction." (PMID 41585791, 2025). "Given the importance of this pathway, the effect on Notch of novel therapeutic approaches against endothelial dysfunction, such as ANGPTL3, will need to be carefully investigated." (PMID 34440201, 2021). "Circulating ANGPTL3 and ANGPTL4 undergo variable changes in obese patients with different metabolic phenotypes; changes in ANGPTL4 relate to endothelial dysfunction, making this protein a possible target for vascular prevention in these patients." (PMID 34440242, 2021).